MDM2 (MDM2 proto-oncogene)
Diseases named in the same sentence as MDM2 in open-access papers (continued):
Sharing a sentence is not in itself a finding about the gene and the disease.
hepatocellular carcinoma (continued). "A group of 119 patients with hepatocellular carcinoma (HCC, 63.45 ± 12.59 year, 26–80) and another of 103 non-HCC controls (56 ± 10.82 year, 22–79) were enrolled to investigate association between MDM2 polymorphisms and susceptibility to develop HCC." (PMID 24708820, 2014). "A significant increase of MDM2 SNP309 G/G and T/G genotypes were observed among hepatocellular carcinoma cases (Odds Ratio, OR = 3.56, 95% Confidence Limits, 95% CI = 1.3-9.7; and OR = 2.82, 95% CI = 1.3-6.4, respectively)." (PMID 21843334, 2011). "As an essential light chain for nonmuscle Myosin II (NMII), MYL6B has key impacts on hepatocellular carcinoma by binding to MDM2." (PMID 33817240, 2020). "One protein member of this pathway, MDM2 Proto Oncogene (MDM2), was stabilized by PVT1 via its interaction with Enhancer Of Zeste 2 Polycomb Repressive Complex 2 Subunit (EZH2) in the setting of hepatocellular carcinoma." (PMID 31710657, 2019). "For instance, hepatocellular carcinoma (HCC) frequently exhibits 2 to 10 fold amplification of oncogenes such as Cyclin D1, CDKN1A, KRAS, and MDM2." (PMID 41515655, 2026). "Mechanistically, our previous research on pancreatic cancer and hepatocellular carcinoma (HCC) demonstrated that MA242 destabilizes the MDM2 protein by shortening its half-life and promoting its degradation through the proteasome." (PMID 40046748, 2025). "Although there was no report regarding the relationship between MDM‐2 genetic polymorphisms and ND or functional outcome after IS, some studies have shown that MDM‐2 polymorphisms may be a risk factor for uterine fibroids and hepatocellular carcinoma." (PMID 31909567, 2021).
gastric cancer (84 papers, 2007 to 2025). A primary or metastatic malignant neoplasm involving the stomach. "In different human populations, an association of increased risk of gastric cancer with the GG genotype of MDM2 was especially evident among H. pylori-infected patients." (PMID 33825941, 2021). "A case-control study among the Iranian gastric cancer population showed that Mdm2 SNIP309 is a risk factor for this cancer with an odds ratio of 2.08 (95% confidence interval = 1.37–4.34)." (PMID 27042174, 2016). "Our results suggest that the MDM2 SNP309 polymorphism is associated with a significantly increased risk of gastric cancer." (PMID 23451111, 2013). "Subsequently, a case-control study including 438 controls and 410 patients with sporadic gastric carcinoma provided evidence supporting the association of MDM2 SNP309 with both an increased susceptibility to gastric carcinoma and poor prognosis." (PMID 24015200, 2013). "In our previous study, we reported that the MDM2 SNP309 (T > G) was associated with gastric carcinoma in Chinese patients, especially those with H. pylori infection." (PMID 23506213, 2013). "Intriguingly, we found that individuals with both MDM2 SNP309G/G and H. pylori infection conferred a synergistic effect for developing gastric carcinoma with an OR of 2.44, suggesting a joint effect between MDM2 polymorphism and H. pylori infection." (PMID 23506213, 2013). "Several studies have investigated the association between MDM2 polymorphism and gastric carcinoma susceptibility." (PMID 23506213, 2013). "In conclusion, the MDM2 SNP309 polymorphism is associated with gastric carcinoma risk and poor prognosis in Chinese patients." (PMID 23506213, 2013). "The Mdm2 SNIP309 G/G homozygous genotype might be a risk factor for gastric cancer and the fact that it is infrequent in Thailand." (PMID 27042174, 2016). "Our results suggest that the MDM2 SNP309 polymorphism may be a low-penetrant risk factor for the development of gastric cancer." (PMID 23451111, 2013). "Therefore, we carried out a meta-analysis on all eligible case-control studies to estimate the overall gastric cancer risk of MDM2 SNP309 polymorphism as well as to quantify the between-study heterogeneity and potential bias." (PMID 23451111, 2013). "Meta-analysis of the MDM2 SNP309 T>G polymorphism on gastric cancer." (PMID 23451111, 2013). "Furthermore, the MDM2 SNP309 polymorphism was associated with a significantly increased risk of gastric cancer in recessive model (GG versus GT/TT, OR = 1.49, 95%CI = 1.30–1.72), but not in dominant model (GG/GT versus TT, OR = 1.18, 95%CI = 0.84–1.65)." (PMID 23451111, 2013). "Recently, a number of studies have reported the role of MDM2 SNP309 polymorphism in gastric cancer risk, but the results are inconclusive, partially because of the possible small effect of the polymorphism on gastric cancer and the relatively small size in each of the published studies." (PMID 23451111, 2013). "We found that the MDM2 SNP309 polymorphism was associated with a significantly increased risk of gastric cancer risk when all studies were pooled into the meta-analysis (GG versus TT, OR = 1.54; 95%CI = 1.04–2.29, and GG versus GT/TT, OR = 1.49, 95%CI = 1.30–1.72)." (PMID 23451111, 2013).
gastric cancer (continued). "So far, no consistent conclusion has been reached on the association between MDM2 polymorphism and gastric carcinoma risk, and there has been only one study reporting that MDM2 polymorphism is associated with both an increased susceptibility and poor prognosis of gastric carcinoma." (PMID 23506213, 2013). "In a study of gastric cancer, MDM2 knockout enhanced chemotherapy sensitivity in a way similar to FRα knockouts." (PMID 38256120, 2024). "MDM2-modulated Sirt6 upregulation and Sirt1 downregulation promoted gastric cancer cell death via increasing ROS accumulation." (PMID 38254877, 2024). "In summary, we found that elevated Sirt6 expression leads to Sirt1 suppression via MDM2, inducing gastric cancer cell death." (PMID 38254877, 2024). "Consistently, previous studies reported that NAT10 can regulate the MDM2 mRNA stability in gastric cancer." (PMID 38331765, 2024). "We showed that Sirt6 upregulates MDM2, which suppresses Sirt1 expression and induces ROS production, thereby promoting gastric cancer cell death." (PMID 38254877, 2024). "MiR-410 inhibits gastric cancer cells proliferation, migration, and invasion by targeting the MDM2 gene." (PMID 37077823, 2023). "The inhibitory effect of GLA on gastric cancer and the expression of MDM2 and RNF6 was also validated in in vivo study." (PMID 35814430, 2022). "Knockdown of FOLRα thus enhanced the sensitivity of gastric cancer cells to cytotoxic chemotherapy to a similar extent as did that of MDM2." (PMID 34185411, 2021). "For instance, miRNA-518 targets MDM2 to inhibit cell growth and induce cell apoptosis in gastric cancer." (PMID 32432654, 2020). "In the current study, we depict an individual with gastric cancer that harbored EGFR as well as MDM2 amplification who had indolent disease; the patient, however, showed explosive progression after being given the anti–PD-1 inhibitor nivolumab." (PMID 30148248, 2018). "We show that CA10 treatment reduces the expression of CDC2, Cyclin B1 and MDM2 confirming G2/M cycle arrest in gastric cancer cells." (PMID 29254150, 2017). "Western blotting analysis also indicated that B19 dose-dependently inhibited the expression of cell cycle-related proteins such as MDM-2, Cyclin B1 and Cdc2 in human gastric cancer cells." (PMID 26919094, 2016). "Western blotting analysis indicated that EF24 treatment also dose-dependently inhibited the expression of cell cycle-related proteins such as MDM2 and Cdc2 in these gastric cancer cells." (PMID 26919110, 2016).
gastric cancer (continued). "In agreement with previous studies, we also found MDM2 SNP309G/G independently predicted poor prognosis of gastric carcinoma." (PMID 23506213, 2013). "MDM2 SNP309G allele is associated with an increased risk and poor prognosis of gastric carcinoma in Chinese patients." (PMID 23506213, 2013). "We also discovered long-range epigenetic silencing (LRES) regions in gastric cancer tissue and identified several hypermethylated genes (MDM2, DYRK2, and LYZ) within these regions." (PMID 22133303, 2011). "Additionally, Sirt1 downregulation and Sirt6 upregulation were detected in the presence of MDM2 in gastric cancer cells." (PMID 38254877, 2024). "The activity of the three proteins, Sirt6, MDM2, and Sirt1, results in increased ROS production, which is responsible for an anti-tumorigenic effect, suggesting that these three molecules are potential targets for the treatment of gastric cancer." (PMID 38254877, 2024). "It is hypothesized that the MDM2 gene could serve as a marker and inhibiter of tumors for the reduced expression of human breast, prostate, and gastric cancers." (PMID 37049742, 2023). "The observed increase in the percentage of apoptosis after the treatment with the indoleamine may have been due to the blockade of the Akt/MDM2 pathway, an effect that was previously observed in gastric cancer cells." (PMID 37107301, 2023). "Thus, we selected Mdm2 and RNF6 in the present study to explore the molecular mechanism underlying the inhibitory effect of GLA in gastric cancer cells." (PMID 35814430, 2022). "The MDM2 level has been found to progressively increase in gastric specimens from normal gastric mucosa, chronic gastritis, intestinal metaplasia, dysplasia, and gastric cancer." (PMID 33825941, 2021). "The enrichment included the PI3K-Akt and IL-17 signaling pathways, and the network analysis showed that the Zhishi-Baizhu herb pair acted on seven key targets, namely, AKT1, MMP9, IL-6, CCND1, BCL2, MTOR, and MDM2 (where they played a role in treating gastric cancer)." (PMID 34899944, 2021). "MiRNA-518 hinders cell proliferation and stimulates apoptosis by modulating MDM2 in gastric cancer." (PMID 32943988, 2020). "We turned the focus on MDM2, since it has been documented that miR-518 could bind to MDM2 and then inhibit proliferation, metastasis and drug-resistance of gastric cancer cells." (PMID 32423468, 2020). "Amplified MDM2 has been reported in > 10% of gastric cancers." (PMID 29716622, 2018).
gastric cancer (continued). "The clinical data concerning the role of Mdm2 SNIP309 in gastric cancer development is limited." (PMID 27042174, 2016). "Moreover, more gene-gene and gene-environment interactions should also be considered in future analysis, which should lead to better, comprehensive understanding of the association between the MDM2 SNP309 polymorphism and gastric cancer risk." (PMID 23451111, 2013). "In summary, this meta-analysis provided evidence of the association between MDM2 SNP309 polymorphism and gastric cancer risk, supporting the hypothesis that the SNP309 polymorphism may be a low-penetrance susceptibility marker of gastric cancer." (PMID 23451111, 2013). "MDM2 SNP309G/G genotype was associated with an increased risk of gastric carcinoma when compared with T/T genotype or T carriers (both P < 0.01), and a joint effect between MDM2 SNP309G/G and H. pylori infection was observed to intensify gastric carcinoma risk." (PMID 23506213, 2013). "Therefore, individuals with both MDM2 SNP309G/G genotypes and H. pylori infection are expected to have a higher risk in development of gastric carcinoma." (PMID 23506213, 2013). "We identified 4 published studies of the MDM2 SNP309 and gastric carcinoma susceptibility." (PMID 23506213, 2013). "It has been reported that MDM2 SNP309 is associated with poor prognosis of different kinds of carcinomas, and that SNPG/G is associated with shortened survival of patients with advanced gastric carcinoma." (PMID 23506213, 2013). "Additional, there is a joint effect of MDM2 SNP309G/G allele and H. pylori infection on gastric carcinoma development, which may attribute to H. pylori LPS." (PMID 23506213, 2013). "Association between MDM2 SNP309 and gastric carcinoma in relation to H." (PMID 23506213, 2013). "For instance, the hTERT/MDM2-FOXO3a-integrin β1 (ITGB1) signaling pathway is implicated in hTERT-stimulated gastric cancer invasion, suggesting that this signaling pathway may be a novel target for the prevention and treatment of gastric cancer metastasis." (PMID 38203812, 2024). "Notably, MDM2 and FRα knockouts increased the sensitivity of gastric cancer to oxaliplatin." (PMID 38256120, 2024). "To identify molecules that contribute to the phenotype of FOLRα‐expressing gastric cancer, we performed immunoblot and microarray analyses focusing on molecules related to cell proliferation or survival, and we found that knockdown of FOLRα resulted in down‐regulation of MDM2 expression." (PMID 34185411, 2021). "The possible mechanisms of the components of the Zhishi-Baizhu herb pair in treating gastric cancer might be related to luteolin and naringenin, which intervened with the targets AKT1, MMP9, IL-6, CCND1, BCL2, MTOR, and MDM2, and are linked with the PI3K-Akt and IL-17 signaling pathways." (PMID 34899944, 2021). "The Mdm2 SNIP309 G/G homozygous genotype might be a risk factor for gastric cancer and the fact that it is infrequent in Thailand could explain to some extent the low incidence of gastric cancer in the Thai population." (PMID 27042174, 2016). "Thus, the aim of this study was to investigate whether MDM2 SNP309 is associated with susceptibility and prognosis of gastric carcinoma in Chinese patients." (PMID 23506213, 2013).